NOD2 (nucleotide binding oligomerization domain containing 2)
Diseases named in the same sentence as NOD2 in open-access papers (continued):
Sharing a sentence is not in itself a finding about the gene and the disease.
inflammatory bowel disease (139 papers, 2006 to 2025). A spectrum of small and large bowel inflammatory diseases of unknown etiology. "The NOD2 gene polymorphism has been previously identified as a susceptibility locus for human inflammatory bowel disease." (PMID 40428307, 2025). "Variants in the NOD2 gene can give rise to a spectrum from inflammatory bowel disease to autoinflammatory disease.This report further raises awareness of the underdiagnosed disease in the medical community." (PMID 39372397, 2024). "Unraveling the role of the PGLYRP-1-based PGN recognition system in inflammatory bowel diseases will be important in the context of diseases associated with NOD2 and GEF-H1 variants." (PMID 39483916, 2024). "Many studies have shown that mutation of NOD2 is closely related to inflammatory bowel disease, intestinal cancer, breast cancer and even endometrial carcinoma." (PMID 36316517, 2023). "TYK2 is essential in JAK/TYK2 signaling of inflammatory bowel disease NOD2 is the first risk gene that has been identified for CD." (PMID 38046046, 2023). "The central role in maintaining the balance between the gut microbiota and the host immune response to control inflammation makes NOD2 one of the most important susceptibility genes for inflammatory bowel diseases." (PMID 36199823, 2022). "NOD2 was identified in a human GWAS as a host gene associated with the microbiome composition and inflammatory bowel disease." (PMID 34159422, 2021). "The association between the NLR NOD2 and inflammatory bowel disease is indicative of the potential ability of NLRs to protect the gut barrier." (PMID 33579281, 2021). "NOD2 regulates bowel microorganisms, provides resistance against infections such as diarrhea, and reduces the risk of inflammatory bowel diseases in humans and mice." (PMID 34573406, 2021). "HCK was previously found to be genetically associated with inflammatory bowel disease and predicted as a causal factor that regulates NOD2, IL10 and ALOX5." (PMID 32565911, 2020). "The NOD1 and NOD2 pathways have been associated with a range of autoimmune disorders, most prominently with inflammatory bowel disease (IBD)." (PMID 31632962, 2019). "We have previously identified NOD2 genotype and inflammatory bowel diseases (IBD) phenotype, as associated with shifts in the ileal microbiome (“dysbiosis”) in a patient cohort." (PMID 30818349, 2019). "For example, inflammatory bowel disease risk loci near NOD2 were also associated with Enterobacteriaceae in patients with inflammatory bowel disease." (PMID 29378630, 2018). "An association has previously been demonstrated between the count of specific risk alleles for inflammatory bowel disease in the host (e.g. NOD2) and an increased relative abundance of Enterobacteriaceae in the intestinal microbiome." (PMID 30037806, 2018). "For example, based on the NOD2-Enterobacteriaceae association found in patients with inflammatory bowel disease, it was calculated that detecting the same association in a genome-wide significant manner would require 3700 patients." (PMID 29378630, 2018). "NOD2 is the major inflammatory bowel disease susceptibility gene with 15%-20% IBD patients carrying mutations in NOD2." (PMID 29379601, 2017). "The genetic risk score representing all known risk alleles for inflammatory bowel disease showed strong association with disease subphenotype (p=1·65 × 10−78), even after exclusion of NOD2, MHC, and 3p21 (p=9·23 × 10−18)." (PMID 26490195, 2016). "Nucleotide-binding oligomerization domain-containing protein 2 (NOD2) signaling in inflammatory bowel disease is typically important for recognizing pathogenic patterns and promotes inflammation to elicit their removal by the immune system." (PMID 26988232, 2016). "NOD2 encodes an intracellular innate immunity sensor, and the NOD2 p.R702W polymorphism is strongly associated with inflammatory bowel disease and bacterial infections." (PMID 26556047, 2015).
inflammatory bowel disease (continued). "NOD2 SNPs are associated with inflammatory bowel disease and share a signaling defect in response to both the Gram-negative cell wall component lipopolysaccharide (LPS) as well as PGN in human experimental studies." (PMID 23691182, 2013). "NOD1+32556 and NOD2+2209, NOD2+2722, and NOD2+3020 SNPs are associated with inflammatory bowel disease and share a signaling defect in response to LPS and PGN." (PMID 22662111, 2012). "The IL23R protective (A) allele and the NOD2 (C) risk allele rs2066845 were associated with a positive family history of inflammatory bowel disease." (PMID 23300620, 2012). "The three NOD2 variant single nucleotide polymorphisms (SNPs) (rs2066844, rs2066845, and rs5743293) have been strongly associated with clinical presentation of inflammatory bowel disease." (PMID 22269043, 2012). "These infection model studies highlight an important role for Nod2 in bacterial pathogen defence, however, in the context of inflammatory bowel disease the commensal microbiota is likely the underlying cause of inflammation." (PMID 22272321, 2012). "The aims were to analyze two novel NOD2 variants (rs2066843 and rs2076756) in a large cohort of patients with inflammatory bowel disease and to elucidate phenotypic consequences." (PMID 21209938, 2010). "NOD2, as a key gene involved in inflammatory responses and regulating autophagy, was the first susceptibility gene identified in association with inflammatory bowel disease." (PMID 40468178, 2025). "NOD2 variants may also decrease the ability of the intestinal wall to respond to LPS, which could be related to inflammatory bowel disease." (PMID 34335253, 2021). "NOD2 deficient expression influences the composition of the microbiota because its absence leads to a higher number of pathogenic bacteria in the gastrointestinal tract and is also involved with the development of inflammatory bowel diseases." (PMID 32986710, 2020). "Polymorphisms in the PRR nucleotide-binding oligomerization domain-containing protein 2 (NOD2) represent the strongest genetic risk factor for the inflammatory bowel disease Crohn's (CD), and thus this bacterial sensor is the focus of particular research interest." (PMID 31379806, 2019). "The identification of disease-causing TRIM22 variants that affect NOD2 signaling could lead to the development of a new diagnostic tool and could offer novel treatment opportunities for patients with very early onset inflammatory bowel diseases." (PMID 31803185, 2019). "NOD2/CARD15 gene polymorphism in patients with inflammatory bowel disease: is Hungary different?" (PMID 28819537, 2017). "Similarly, the NOD2 polymorphism present in our patient has been closely linked with microbiota alterations and the development of inflammatory bowel disease." (PMID 26556047, 2015). "Only rarely does a SNP have a clear mechanistic relationship, such as when the polymorphism lies in the coding sequence of a gene and alters protein function, as has been observed with NOD2 (nucleotide-binding oligomerization domain containing-2) mutations in inflammatory bowel disease." (PMID 23755065, 2012). "Abnormal expression of NOD2 has been implicated in inflammatory bowel disease." (PMID 21901105, 2011). "The significance of this association may differ according to the population studied and the type of inflammatory bowel disease, as also demonstrated for the NOD2/CARD15 gene polymorphisms." (PMID 19568552, 2009). "Mutations in NOD2 have been associated with granulomatous autoinflammatory conditions, including Blau syndrome (BS), inflammatory bowel disease (IBD), and NOD2-associated autoinflammatory disease (NAID)." (PMID 41357180, 2025). "In CD, the NOD2 gene on chromosome 16 and several additional risk variants identified through genome-wide association studies (GWAS)—with key insights from the International Inflammatory Bowel Disease Genetics Consortium—have enhanced our understanding of the pathobiology of the disease." (PMID 40399663, 2025).
inflammatory bowel disease (continued). "Dysregulation of NOD1 and NOD2 signaling has been implicated in inflammatory bowel diseases (IBD), metabolic syndrome, and other immune-related disorders." (PMID 40635891, 2025). "The NOD2 signaling pathway, which plays an important role in the mechanisms of inflammatory bowel disease (IBD) development, has been closely associated with ubiquitination." (PMID 39420190, 2024). "Mutations in the NOD2 gene are responsible for the high risk of developing inflammatory bowel disease (IBD), particularly Crohn’s disease." (PMID 39125905, 2024). "The current study showed that DEGs in chicken jejuna between LPC-treated groups and the control enriched in NLR signaling pathway which agree with the research that NLRs might function as the intestinal barrier guardian, given their association with NOD2 and inflammatory bowel disease." (PMID 35795789, 2022). "Allelic variation at genes such as NOD2, encoding the intracellular PRR Nucleotide Binding Oligomerization Domain Containing 2, is strongly associated with susceptibility or resistance to inflammatory bowel disease (IBD)." (PMID 35572569, 2022). "NOD1 and NOD2 dysfunction are associated with other chronic inflammatory diseases, such as inflammatory bowel disease (IBD), asthma, arthritis, and periodontitis." (PMID 33503814, 2021). "Moreover, several studies have demonstrated that the susceptibility to inflammatory bowel diseases is related to NOD2 deficiency, what led us to investigate the role of NOD2 in the development of morphological inflammatory-induced alterations of the digestive system in Chagas’ disease." (PMID 32986710, 2020). "Mutations in the peptidoglycan sensor NOD2 locus represent one of the most important genetic risk factors for inflammatory bowel disease (IBD)." (PMID 33117398, 2020). "Loss of function mutations in NOD2 result in impaired autophagy and have been associated with inflammatory bowel disease (IBD), a condition characterized by heightened production of proinflammatory cytokines and often associated with ND comorbidity." (PMID 31139187, 2019). "For example, NOD1 and NOD2 have been implicated in the pathogenesis of inflammatory bowel disease (IBD)." (PMID 28955343, 2017). "The association of Nod2 genotype (and other host polymorphisms) and environmental factors likely combine to influence the ecological succession of the tissue-associated microflora accounting in part for their association with the pathogenesis of inflammatory bowel diseases." (PMID 22272321, 2012). "Loss of function NOD2 variants are highly associated with inflammatory bowel disease (IBD) risk, which may be due to defects in barrier function resulting from strong Th1 responses." (PMID 40426880, 2025). "X-linked inhibitor of apoptosis protein (XIAP) deficiency is a severe immunodeficiency with clinical features including hemophagocytic lymphohistiocytosis (HLH) and inflammatory bowel disease (IBD) due to defective NOD2 responses." (PMID 36329240, 2023). "For example, mutations in NOD2, a well-characterized PRR, is significantly associated with the inflammatory bowel disease (IBD)." (PMID 37191444, 2023). "Although many NOD2 studies have focused on inflammatory bowel disease, it has been shown that NOD2 is involved in the inflammatory response after cerebral ischemia, triggering an excessive inflammatory response and exacerbating brain injury." (PMID 37077541, 2023). "The polymorphisms of NOD2 are investigated as a risk factor for Inflammatory bowel disease (IBD)." (PMID 36506547, 2022). "One of the susceptibility genes of inflammatory bowel disease (IBD) is NOD2." (PMID 32824515, 2020). "Previous studies in mammals have shown that, in addition to its role in the activation of cytosolic antibacterial signaling, NOD2 also plays an essential role in the prevention of inflammatory bowel disease (IBD)." (PMID 29872030, 2019).
inflammatory bowel disease (continued). "The action of NOD2 and its receptor for bacterial pattern recognition offers a valuable link to inflammatory bowel diseases." (PMID 31723489, 2019). "Furthermore, the NOD2 pathway is specifically related to inflammatory bowel disease (IBD) as a large number of IBD patients harbor NOD2 mutations." (PMID 30200338, 2018). "Three loci (NOD2, MHC, and MST1 3p21) were associated with subphenotypes of inflammatory bowel disease, mainly disease location (essentially fixed over time; median follow-up of 10·5 years)." (PMID 26490195, 2016). "This study illustrating inhibition of de novo sphingolipid synthesis with myriocin suppressed Salmonella-induced NOD2-mediated hBD-2 expression, links the relationship between membrane sphingolipids and inflammatory bowel diseases." (PMID 26893616, 2016). "Given that NOD2 variants still represent the most important predictors for CD susceptibility and phenotype, we evaluated the association of rs72796353 with inflammatory bowel disease (IBD) susceptibility and the IBD phenotype." (PMID 26147989, 2015). "Aberrant triggering of Nod2 can lead to the development of inflammatory bowel diseases such as ulcerative colitis or Crohn's disease (CD)." (PMID 25423082, 2014). "In patients with chronic inflammatory diseases, aberrant expression and function of NOD2 has been reported mainly in inflammatory bowel disease and other inflammatory disorders." (PMID 21886831, 2011). "Upon activation, dectin-1 signaling converges, similar to NOD2, on the adaptor molecule CARD9 which is associated with inflammatory bowel disease (IBD)." (PMID 19915667, 2009). "Additionally, the immune-regulatory genes NOD2 and CARD9 are associated with shifts in Enterobacteriaceae populations, particularly in individuals predisposed to inflammatory bowel disease (IBD)." (PMID 40430189, 2025). "<article data-scroll-anchor=”false” data-testid=”conversation-turn-3” data-turn=”user” dir=”auto” tabindex=”-1”> This study identifies a critical interaction between GIV and NOD2 in gut macrophages, revealing their importance in maintaining gut health and preventing inflammatory bowel diseases." (PMID 41321314, 2025). "In addition, we discuss the clinical relevance of the NOD2-mediated negative regulation of TLRs in inflammatory bowel disease." (PMID 39403381, 2024). "Particular attention is paid to NOD2 due to its involvement in inflammatory bowel disease (IBD)." (PMID 38867324, 2024). "Recently, researchers have observed the role of autophagy in dendrite epithelial cell communication, adaptive immunity response, NOD2-directed bacteria sensing, lysosome destruction, and immune-mediated clearance to be important for inflammatory bowel disease (IBD) pathogenesis." (PMID 31683886, 2019). "There are also reports that CARD15/NOD2 dysfunction may cause immunoregulatory dysfunction of the innate immune response, which may also lead to the development of inflammatory bowel disease." (PMID 30648106, 2018). "Moreover, miR-146a-mediated NOD2-SHH signaling regulates gut inflammation in murine model of inflammatory bowel diseases." (PMID 29166940, 2017). "Many studies, especially the early ones, studied only NOD2 and HLA, and none included genetic variants not previously implicated in risk for inflammatory bowel disease." (PMID 26490195, 2016). "Defective NOD2 responses have established links to inflammatory bowel diseases (IBD)." (PMID 25666722, 2015). "The involvement of NOD2 signaling in the intensity of inflammatory responses is not unexpected as polymorphisms in NOD2 are closely linked to the pathogenesis of inflammatory bowel disease, another example of a pathological response to mucosal bacteria." (PMID 24586160, 2014). "However, during DSS-induced colitis, the murine model of inflammatory bowel disease (IBD) that is driven by the microbiota, NOD1/NOD2-deficiency led to greater susceptibility to colitis." (PMID 24381573, 2013).
inflammatory bowel disease (continued). "IECs and small intestinal Paneth cells express NOD2, observed at higher levels in Paneth cells of inflammatory bowel disease (IBD) patients." (PMID 38736751, 2024). "The relevance of Nod2 to inflammatory diseases, primarily inflammatory bowel disease (IBD), was demonstrated almost two decades ago17,18 and have been followed by numerous studies, but the mechanism of the effect of Nod2 on colitis remains obscure." (PMID 33239685, 2020). "Similarly, NOD2 (CARD15) LOF polymorphisms are associated with an increased risk of clinical allergy and inflammatory bowel disease (IBD), whereas activating mutations cause the autoinflammatory disease Blau syndrome." (PMID 35281022, 2022). "In addition, a previous study has reported that reactive oxygen species (ROS)-mediated NOD2 activation further impairs epithelial barrier function in inflammatory bowel disease (IBD)." (PMID 33670592, 2021). "Importantly, this CD versus UC score retained significance even after NOD2, MHC, and MST1 were removed, lending support to the notion that the genetic risk score offers more information about the genetic substructure of inflammatory bowel disease than individual SNP associations alone." (PMID 26490195, 2016). "Essential roles include the immune genes (e.g., TLRs, NOD2, IL-10) in regulating microbial populations and maintaining barrier integrity, hence establishing a clear connection between dysbiosis and inflammatory disorders such as inflammatory bowel diseases (IBD)." (PMID 41246320, 2025). "The Inflammatory Bowel Disease (IBD) Panel, which includes NOD2, IL23R, and ATG16L1 genes along with CYP2C19, which are associated with IBD severity and susceptibility can aid in defining genetic risk and tailoring treatment for patients suffering from Crohn’s disease and ulcerative colitis." (PMID 38420192, 2024). "Indeed, human IECs constitutively express TLR3, TLR5, TLR9, NOD1, NOD2 and low levels of TLR2 and TLR4, where TLR4 is increased in inflammatory bowel disease (IBD) IECSs and intestinal macrophages." (PMID 36296363, 2022). "Our findings indicates that the ITSN1-2/ceRNA axis may serve as a therapeutic target in NOD2/RIP2-driven diseases (e.g., cancer, RA, inflammatory bowel disease), but its inverse regulation in other disease like in SLE underscores the need for disease-specific biomarker panels." (PMID 40629453, 2025). "In addition, the researchers found that variants in TRIM22 influenced the activation of NOD2-dependent IFN-β signaling and the upregulation of NF-κB pathways in early-onset inflammatory bowel disease, and the TRIM22-NOD2 network affected antiviral pathways leading to inflammation." (PMID 35609018, 2022). "We previously examined the effects of the NOD2 and ATG16L1 polymorphisms on ileal microbial composition in 1) ileal CD subjects undergoing initial ileal resection, 2) IBD colitis without ileitis (predominantly ulcerative colitis) subjects and 3) subjects without inflammatory bowel disease (non-IBD)." (PMID 30818349, 2019).